GPN3 (GPN-loop GTPase 3)
Description:
Small GTPase involved in the correct assembly of RNA polymerase II (RNAPII) complex, ensuring proper nuclear import of RNAPII.
Synonyms: ATPBD1C; MGC14560
Tractability: PROTAC: ubiquitination databases record sites on it.
Gene: Protein-coding gene on chromosome 12 (110,452,486 to 110,469,268, reverse strand). Ensembl gene ENSG00000111231.
Subcellular location: Cytoplasm; Nucleus
Subcellular location (Human Protein Atlas): Nuclear speckles; Cytosol
Gene Ontology:
Molecular function: protein binding; GTPase activity
Biological process: protein import into nucleus
Cellular component: cytoplasm; nucleus; protein-containing complex
Genetic constraint (gnomAD): Loss-of-function variants: 10 observed, 8.61 expected, observed/expected ratio (o/e) 1.16, 90% interval 0.71 to 1.81. That is too few expected variants to judge how well the gene tolerates losing a copy. Missense variants: 76 observed, 85.81 expected, observed/expected ratio (o/e) 0.89, 90% interval 0.74 to 1.07. Synonymous variants: 29 observed, 33.23 expected, observed/expected ratio (o/e) 0.87, 90% interval 0.65 to 1.19.
Homologues: Orthologues: macaque GPN3 (99% identical), guinea pig GPN3 (97% identical), rat Gpn3 (96% identical), rabbit GPN3 (96% identical), chimpanzee GPN3 (95% identical), mouse Gpn3 (95% identical), pig GPN3 (92% identical), dog GPN3 (90% identical), tropical clawed frog gpn3 (85% identical), zebrafish gpn3 (85% identical), Drosophila melanogaster CG2656 (52% identical), Caenorhabditis elegans gex-4 (51% identical). Paralogues in human: GPN2 (40% identical), GPN1 (25% identical).
Diseases named in the same sentence as GPN3 in open-access papers:
GPN3 is named in the same sentence as 5 diseases in open-access papers, as found by Europe PMC text mining. Sharing a sentence is not in itself a finding about the gene and the disease. The quoted sentences say what the papers report.
breast carcinoma (2 papers, 2023 to 2025). "To date, only two studies have reported an association between GPN3 and cancer progression, demonstrating its role in regulating drug resistance in small cell lung cancer cells and promoting breast cancer cell proliferation." (PMID 39893205, 2025). "However, to date, only two publications have demonstrated that constitutively activated GPN3 confers protection against chemoresistant small cell lung cancer cells and promotes proliferation of breast cancer cells." (PMID 39893205, 2025).
non-small cell lung carcinoma (1 paper, 2025). A group of at least three distinct histological types of lung cancer, including non-small cell squamous cell carcinoma, adenocarcinoma, and large cell carcinoma. "Furthermore, our findings indicate that aberrant overexpression of GPN3 is observed in non-small cell lung cancer (NSCLC) tissues compared to adjacent normal tissues, and high expression levels of GPN3 are associated with poor prognosis for NSCLC patients." (PMID 39893205, 2025).
cancer (3 papers, 2021 to 2025). A tumor composed of atypical neoplastic, often pleomorphic cells that invade other tissues. "In line with a role for GPN3 in RNA pol II transport to the nucleus, the Q279∗ mutation of GPN3, related to cancer, has been described to lead to GPN3 entering the cell nucleus and inhibiting GPN1 nuclear export." (PMID 34026841, 2021). "For instance, as neutrophils are immune cells and serve as the first responders to inflammation, it remains unknown whether GPN3 influences the tumor microenvironment and mediates cancer metastasis by regulating neutrophil degranulation." (PMID 39893205, 2025). "GPN3 is evolutionarily conserved across eukaryotic cells, ranging from archaea to humans, indicating that it has fundamental cellular functions in human health and diseases, including cancers." (PMID 39893205, 2025). "While GPN3 mutations are known to cause significant functional changes in various cancers, the expression, prognostic relevance, and biological function of GPN1 in human cancers—particularly in HCC—remain unclear." (PMID 39524004, 2025).
tumor diseases (1 paper, 2025). "Nevertheless, further investigations are warranted to elucidate the involvement of GPN3 in other tumor types as well as non-tumor diseases." (PMID 39893205, 2025). "Additionally, further investigation is required to verify if GPN3 modulates tumor angiogenesis through manipulation of VEGFA-VEGFR2 signaling, a crucial positive regulator of angiogenesis." (PMID 39893205, 2025). "Moreover, confirmation is needed regarding whether GPN3 plays a role in tumor metabolic reprogramming by involvement in carbohydrate metabolism or monocarboxylic acid metabolic processes." (PMID 39893205, 2025).
GPN3 also shares sentences with these, for which no sentence is quoted: small cell lung carcinoma (1 paper).